LEP (leptin)
Diseases named in the same sentence as LEP in open-access papers (continued):
Sharing a sentence is not in itself a finding about the gene and the disease.
Obesity (continued). "While the precise connection between obesity and erectile dysfunction (ED) remains unclear, the role of obesity in metabolic syndrome suggests that ED may be caused by underlying pathophysiological processes, including oxidative stress, inflammation, and insulin and leptin resistance." (PMID 39402470, 2024). "Leptin resistance represents a pivotal pathophysiological aspect of obesity, characterized by an impairment in the ability of the CNS to respond to leptin." (PMID 39594988, 2024). "Dietary factors, particularly HFDs, exacerbate inflammation and impact leptin levels, thereby influencing obesity-related metabolic disorders." (PMID 39700087, 2024). "Statistically highly significant differences in the anthropometry, body composition parameters: and obesity-related biomarkers (Leptin, ALT, and AST) between the pre and post-follow-up measurements at the end of the study as they were all decreased." (PMID 38744950, 2024). "More specifically, studies propose that obesity, as expressed by an increased BMI, directly influences the immune system via the actions of specific hormones, including adiponectin and leptin, thereby fostering a pro-inflammatory environment." (PMID 38541964, 2024). "In young adults with obesity, plasma leptin levels were 2.6 times higher and GLP-1 levels were 90% higher compared to those with a lean body type." (PMID 38673991, 2024). "Serum leptin is typically present in direct proportion to the amount of adipose tissue, and thus, it is increased in obesity." (PMID 38732558, 2024). "Another instance of shared genetic factors between obesity and neurodegenerative diseases involves leptin and its receptor, LEPRβ." (PMID 39273520, 2024). "Circulating leptin levels increase in proportion to adipose tissue mass, which can result in a state of leptin resistance in obesity." (PMID 39339770, 2024). "Another common metabolic change observed in obesity is increased leptin concentration in the plasma." (PMID 37237937, 2023). "Monogenic obesity is a type of rare and severe early-onset obesity, resulting from a single mutation of a gene such as MC4R, LEP, LEPR, and POMC primarily involved in the leptin–melanocortin pathway." (PMID 37327085, 2023). "Subsequently, we widely contributed to show that perinatal leptin intake can protect against obesity, but also against the MONW phenotype in adult rats." (PMID 38203399, 2023). "Recent studies have shown that circulating leptin levels are elevated in obese patients, suggesting a link between obesity and postoperative lymphedema." (PMID 37373485, 2023). "Obesity resulting from the HF diet feeding in this study was mirrored by an enhanced leptin level in WKY rats 60 and 66 weeks old, before and at the end of the experiment, respectively." (PMID 36678151, 2023). "Eighth, we demonstrated that FCPs significantly promote the gene expression levels of leptin, which is one of the best-known hormone markers for obesity and exerts an important role in both prenatal and postnatal T-cell development in the thymus." (PMID 37888466, 2023). "In obesity, leptin resistance promotes significantly elevated serum leptin levels, which has pro-inflammatory consequences further worsening metabolic endotoxemia in these individuals." (PMID 37571301, 2023). "This review is a collection of different studies and an analysis of information obtained on the relationship between obesity and cancer and obesity and leptin in the last few decades." (PMID 37509120, 2023). "Estrogen contributes to obesity by influencing the synthesis of leptin, thus affecting the regulation of appetite and fat deposition." (PMID 37626804, 2023). "As a result, mice were more prone to obesity, exhibiting a decrease in energy expenditure, impaired glucose tolerance, insulin and leptin resistance, and increased food intake." (PMID 37582706, 2023).
Obesity (continued). "In discussing adiponectin and leptin, we again focused on the molecular mechanisms carefully explaining the highly complex relationships between obesity and dementia." (PMID 37363537, 2023). "The levels of leptin increase in correlation with fat mass in individuals with obesity, which is recognized for its ability to regulate neuropeptides in the hypothalamus, thereby controlling food intake." (PMID 38058391, 2023). "Although rs10487505 also influences obesity-related parameters in men, its effect on leptin and BMI seems to be found only in women." (PMID 36833305, 2023). "There is a correlation between obesity and increased AT leptin secretion, with leptin enhancing the secretion of exosomes from breast cancer cell lines, which promotes oxidative metabolism and angiogenesis in the receiving cells." (PMID 37289328, 2023). "PBDE accumulation was found to have links to certain obesity biomarkers such as leptin and adiponectin, as well as increased PPAR-γ expression." (PMID 37240215, 2023). "Decreased circulating leptin levels are also thought to underpin a significant proportion of cases of polygenic obesity, which has prompted genome-wide searches for physiological regulators of leptin expression." (PMID 37047583, 2023). "As an adipocyte-derived peptide and a regulator of food intake and energy expenditure, Leptin is related to short sleep duration in the pathophysiology of obesity and accordingly type 2 diabetes." (PMID 37546325, 2023). "The genetically induced hyperphagia and obesity in leptin- and leptin receptor-knockout mice, as well as in Zucker obese rats, are associated with the development of insulin resistance, T2DM, and abnormal leptin signaling." (PMID 36674935, 2023). "The levels of serum visfatin, resistin and leptin in the obesity group were higher than those in other groups." (PMID 37231396, 2023). "To determine the biological consequence(s) of obesity on CHIP-bearing HSC/Ps, we generated obese FBM (leptin-deficient Ob/Ob) mice possessing Tet2–/– or Dnmt3a+/– mutations to mimic the human pre-leukemic condition in the context of obesity." (PMID 37071471, 2023). "According to the early hypothesis, obesity occurs due to hypothalamic dysregulation of food intake and energy homeostasis caused by dysregulation of the adipokine leptin and decreased tissue sensitivity to its action, and hyperleptinemia and leptin resistance develop with increasing age." (PMID 38068822, 2023). "We recently showed that obesity enhances PD-1 mediated T-cell dysfunction at least partly by leptin signaling." (PMID 37225730, 2023). "Polymorphisms in the LEP and LEPR genes are increasingly being studied in conjunction with LEP levels, to provide insight into their roles in obesity-mediated cancers, although data directly linking LEP and LEPR genetic variations to CRC are limited." (PMID 37282602, 2023). "Obesity appears to determine an increase in PD-1 expression, induces T-cells to release more PD-1 protein, and increases the secretion of adiponectin and leptin from adipose tissue." (PMID 37569757, 2023). "In obese animals, Zn supplementation can alleviate obesity, enhance insulin sensitivity, and reduce leptin levels." (PMID 36977735, 2023). "The imbalance between leptin and adiponectin plays an important role in the obesity–cancer relationship." (PMID 37686769, 2023). "Zn is a trace element involved in the metabolism of obesity-related hormones like insulin, leptin, and thyroid hormones and has a role in most metabolic pathways." (PMID 37513551, 2023). "Measurement of MI and intake of leptin need to be carried out; however, this will likely be fraught with additional lactation issues experienced by women with obesity, such as low milk supply, leading to supplementation." (PMID 37242254, 2023). "Conversely, overexpressing SH2B1 enhances leptin sensitivity, suggesting its potential as a therapeutic target for obesity." (PMID 38027481, 2023).
Obesity (continued). "In the mouse model, elafin seems to increase serum leptin levels and regulate food consumption, thereby inhibiting obesity, hyperglycemia, and liver steatosis." (PMID 37883447, 2023). "In contrast, switching to a healthy maternal diet during lactation, despite maintaining maternal obesity, was able to offset such reduction in the effects of leptin, particularly in males." (PMID 36771278, 2023). "Leptin was initially found to control energy homeostasis through the hypothalamus and was given a high hope for treating obesity." (PMID 37650871, 2023). "In OVX- and HFD-induced obese mice, loganin attenuated the representative obesity phenotypes, including hepatic steatosis, adipocyte hypertrophy, and increased plasma levels of leptin and insulin." (PMID 36902181, 2023). "Taking these findings together, we propose that WKYMVm effectively alleviates the ‘overload’ of leptin signalling and can exert significant control over excessive appetite induced by obesity." (PMID 37603580, 2023). "Nonetheless, a more cohesive correlation has been established between the increased expression of adipokines, in particular leptin, in individuals with obesity and the development and progression of PCa." (PMID 38068717, 2023). "Obesity increases inflammatory adipokines such as leptin while decreases anti-inflammatory adipokines such as adiponectin." (PMID 37789370, 2023). "Recent studies show that the mechanisms contributing to the obesity of OLETF rats are leptin-independent and involve hypothalamic NPY neurons." (PMID 37298724, 2023). "Studies have confirmed that, in the neurons of the hypothalamus in mice, SOCS3 knockout leads to an improvement in central leptin signaling and reduced obesity." (PMID 36899905, 2023). "Leptin level is increased in obesity to correspond with cardiac hypertrophy by binding of leptin to the short form of the leptin receptor in rat hearts." (PMID 37608837, 2023). "Although the molecular mechanism underlying leptin and insulin resistance in obesity is still incompletely understood, protein-tyrosine phosphatase (PTP) 1B has been demonstrated as a major negative regulator of insulin and leptin sensitivity." (PMID 36649358, 2023). "Higher leptin levels in females have been suggested to contribute to greater leptin sensitivity, potentially providing a protective effect against obesity." (PMID 37629396, 2023). "Resistance is characterized by a lack of anorexigenic response despite high levels of circulating leptin and can either be primary or secondary to the development of obesity." (PMID 37064917, 2023). "There is evidence in populations with obesity that leptin appears to activate a pathway that inhibits the renal enzyme responsible for the active form of vitamin D production." (PMID 37189944, 2023). "In patients with obesity and psoriatic patients, leptin levels were found to be significantly increased, with a high level of leptin being directly correlated with BMI and with the PASI score." (PMID 37630719, 2023). "As already shown, obesity is usually accompanied by hyperleptinemia, which leads to a stage of systemic leptin resistance." (PMID 37233170, 2023). "By various studies it has been identified that elevated SNA is observed in obesity, especially in the kidney and hindlimb, for which a leptin increase and hypothalamic melanocortin activity elevation are predominant activities." (PMID 36899905, 2023). "Altogether, these findings demonstrate that T cell-specific leptin signaling is required for some of the changes in CD4+ T cell metabolism and function observed in obesity but has minimal effects on obesity-associated systemic metabolism." (PMID 37276236, 2023). "Post-partal women with obesity had significantly higher leptin levels than the other two groups (obesity: 32.52 ± 10.57 ng/mL vs. RYGB: 15.32 ± 10.11 ng/mL, adj." (PMID 37299461, 2023).
Obesity (continued). "Obesity can also affect bone metabolism directly or indirectly through cytokines secreted by adipocytes such as leptin and adiponectin." (PMID 37559054, 2023). "Another factor involved in the pathogenesis of gallstones is leptin, which is involved in the development of hyperleptinemia when obesity occurs." (PMID 37964952, 2023). "Obesity with visceral fat accumulation, which increases the levels of leptin, TNFα, IL-6 and resistin, and decreases the level of adiponectin, is related to cancer risk and mortality." (PMID 36879265, 2023). "The discovery of the leptin gene and its role in obesity has led to the development of leptin therapy." (PMID 37937009, 2023). "In contrast, mice with the genetic ablation of Ppara on the leptin mutant background showed worsened obesity, increased fat accumulation, and more severe hepatic steatosis compared to leptin mutant mice." (PMID 36599953, 2023). "Leptin induces Th1 cytokine production, while adiponectin expression, which diminishes inflammatory response, is decreased in patients with obesity." (PMID 37515062, 2023). "The present study aimed to investigate the levels of leptin, leptin SR and their correlation with lipid profile, obesity and glycemic control in patients with T2DM." (PMID 36950695, 2023). "The current challenge nowadays is restoring leptin sensitivity by the future application of new-generation leptin analogs and enhancing leptin-related thermogenic responses in obesity." (PMID 36674935, 2023). "Genetic studies have shown that leptin's ability to reduce obesity depends on the JAK2/STAT3 pathway." (PMID 37789370, 2023). "C. odorata and coumarin improved obesity and dyslipidemia through the modulation of adipocytokines (leptin, adiponectin, chemerin), inhibition of HMG-CoA reductase, and attenuation of the lipid profile." (PMID 37033655, 2023). "The main strength of our article is that it was conducted on a very narrow topic with specific goals, that is to find the link between obesity and dementia via adiponectin and leptin." (PMID 37363537, 2023). "To investigate the role of the effect of NAD+ precursor supplementation on obesity, we evaluated leptin and adiponectin." (PMID 37854354, 2023). "A study reported that plasma hormones such as leptin and melatonin influence the development and regulation of obesity." (PMID 37508610, 2023). "The patients showed typical signs of obesity-associated low-grade chronic inflammation characterized by elevated CRP, fibrinogen, and leptin levels and decreased levels of adiponectin." (PMID 37266430, 2023). "Leptin concentration in blood is positively correlated with the amount of adipose tissue, hence increased leptin levels are encountered in people with obesity." (PMID 37047363, 2023). "The contribution of impaired ciliary signaling to obesity via disrupted energy expenditure suggests that primary cilia are important for hypothalamic responses to leptin." (PMID 37064917, 2023). "Obesity indices, body composition, appetite status, and serum levels of leptin and adiponectin were assessed before and after the intervention." (PMID 37476001, 2023). "Further studies, including data regarding these hormones, are needed to gain further knowledge about the influence of gender and menopausal status on leptin and obesity through rs10487505." (PMID 36833305, 2023). "Obesity (characterized by high levels of serum leptin) is functionally incriminated in the pathogenesis of chemoresistance of PDAC." (PMID 37444627, 2023). "Obesity results in cross-talks between leptin, ER-α receptor, IGF signalling and the transactivation of EGFR, which is thought to increase the risk of postmenopausal breast cancer." (PMID 37047163, 2023). "Among various adipokines, adiponectin, leptin, resistin, and visfatin are considered to have the greatest relevance to obesity-related cancer." (PMID 36830834, 2023).
Obesity (continued). "In fact, leptin is a biomarker for obesity management therapies as leptin resistance is related to obesity and leptin levels vary with dieting regimens." (PMID 37647301, 2023). "Leptin concentrations ranging from 200 to 800 ng/mL, corresponding to the serum level of leptin in mouse models of obesity, were tested in this study." (PMID 37895840, 2023). "Studies have shown that obesity-related asthma is more prevalent in women than in men, and the correlation between leptin and asthma is stronger in women than in men." (PMID 37488474, 2023). "Leptin analogs and MC4R agonists are novel therapies that target genetic or hormonal causes of obesity." (PMID 37937009, 2023). "In this regard, changes in insulin levels/sensitivity in patients with obesity correlated with DNA methylation in the promoter of the leptin gene." (PMID 36674935, 2023). "Neurohumoral activation also plays a role in the pathogenesis of obesity and metabolic syndrome through the production of adipokines such as adiponectin and leptin." (PMID 36830844, 2023). "Prolonged exposure to HFD in rodents also leads to hypothalamic inflammation, resulting in hypothalamic leptin resistance and subsequent development of obesity due to reduced leptin effectiveness." (PMID 37957462, 2023). "Heightened leptin levels identified in individuals with obesity are posited to constitute a component of the chronic inflammation mechanism observed in this population, as previously discussed." (PMID 38068717, 2023). "Despite higher values of circulating leptin, its levels in cerebrospinal fluid (CSF) appear to be lower in obesity, suggesting impaired transport across the BBB and a mechanism for leptin resistance." (PMID 38026693, 2023). "Recent approaches in leptin use include identifying individuals with common obesity who have low leptin levels and more room for leptin to act when its levels are raised from low (below physiological level) to normal." (PMID 37371552, 2023). "After sleeve gastrectomy, rats with diet-induced obesity exhibited reduced markers of adiposity (body weight, whole-body adiposity and the adipokine leptin) as well as an improved insulin sensitivity." (PMID 37274331, 2023). "There are significant links between the leptin hormone, a product of the obesity gene, and the development of ovarian cancer." (PMID 37155466, 2023). "In contrast, the experimental elimination of the neonatal LS via leptin antagonists leads to long-term leptin resistance and diet-induced obesity later in life." (PMID 37233672, 2023). "Adipose tissue can also produce adipocytokines such as leptin and adiponectin which play an important role in controlling metabolic processes synergistically or antagonistically, especially in obesity." (PMID 37104164, 2023). "SOCS3 is part of the natural feedback loops controlling leptin signaling, and is a strong mediator of leptin and insulin resistance in obesity." (PMID 36674520, 2023). "This suggests that a factor alternative to EPO is involved in the stimulation of erythropoiesis in obesity, with a prominent candidate being leptin, which is produced by adipose tissue." (PMID 37528422, 2023). "In situations of obesity, the ratio of leptin in serum/cerebrospinal fluid decreases, showing impaired transport." (PMID 36674935, 2023). "In the context of obesity, the secretion patterns of adipokines, notably leptin and adiponectin, experience significant changes." (PMID 38264286, 2023). "In obesity, increased levels of leptin and decreased production of adiponectin, an anti-inflammatory hormone that protects against the development of insulin resistance and diabetes, have been observed." (PMID 37510734, 2023). "In similar pre-clinical models, the authors found that leptin signaling, a hormone produced by adipose tissue and positively correlated with obesity, in obese models increased PD-1 expression and promoted T-cell exhaustion." (PMID 37947629, 2023).